ITPR1 (inositol 1,4,5-trisphosphate receptor type 1)
Description:
Inositol 1,4,5-trisphosphate-gated calcium channel that, upon inositol 1,4,5-trisphosphate binding, mediates calcium release from the endoplasmic reticulum (ER). Undergoes conformational changes upon ligand binding, suggesting structural flexibility that allows the channel to switch from a closed state, capable of interacting with its ligands such as 1,4,5-trisphosphate and calcium, to an open state, capable of transferring calcium ions across the ER membrane (By similarity). Cytoplasmic calcium released from the ER triggers apoptosis by the activation of CAMK2 complex (By similarity). Involved in the regulation of epithelial secretion of electrolytes and fluid through the interaction with AHCYL1 (By similarity). Part of a complex composed of HSPA9, ITPR1 and VDAC1 that regulates mitochondrial calcium-dependent apoptosis by facilitating calcium transport from the ER lumen to the mitochondria intermembrane space thus providing calcium for the downstream calcium channel MCU that directly releases it into mitochondria matrix (By similarity). Regulates fertilization and egg activation by tuning the frequency and amplitude of calcium oscillations (By similarity).
Synonyms: InsP3R1; IP3R1; ACV; PPP1R94; CLA4; IP3R; SCA15; SCA16; SCA29
Tractability: Small molecule: a high-quality ligand is known; it belongs to a druggable protein family. Antibody: UniProt predicts a signal peptide or a membrane-spanning region; its Gene Ontology location is reachable by antibodies, with medium confidence. PROTAC: UniProt records ubiquitination sites on it; ubiquitination databases record sites on it; its protein half-life has been measured; a small molecule that binds it is known.
Target class: Ion channel; Ligand-gated ion channel; IP3 receptor
Gene: Protein-coding gene on chromosome 3 (4,493,345 to 4,847,506, forward strand). Ensembl gene ENSG00000150995.
Subcellular location: Endoplasmic reticulum membrane; Cytoplasmic vesicle, secretory vesicle membrane; Cytoplasm, perinuclear region
Subcellular location (Human Protein Atlas): Vesicles
Pathways (Reactome):
Immune System: Antigen activates B Cell Receptor (BCR) leading to generation of second messengers; CLEC7A (Dectin-1) induces NFAT activation; FCERI mediated Ca+2 mobilization; Role of phospholipids in phagocytosis
Signal Transduction: Ca2+ pathway; DAG and IP3 signaling; PLC beta mediated events; VEGFR2 mediated cell proliferation
Hemostasis: Effects of PIP2 hydrolysis; Elevation of cytosolic Ca2+ levels; cGMP effects
Metabolism: Glucagon-like Peptide-1 (GLP1) regulates insulin secretion; Regulation of insulin secretion
Disease: FCGR3A-mediated IL10 synthesis
Muscle contraction: Ion homeostasis
Gene Ontology:
Molecular function: calcium channel inhibitor activity; inositol 1,4,5-trisphosphate-gated calcium channel activity; protein binding; calcium ion binding; calcium ion transmembrane transporter activity; inositol 1,4,5 trisphosphate binding; intracellularly gated calcium channel activity; phosphatidylinositol binding; calcium channel activity; inositol 1,4,5-trisphosphate receptor activity involved in regulation of postsynaptic cytosolic calcium levels; monoatomic ion channel activity; protein domain specific binding; protein homodimerization activity
Biological process: negative regulation of calcium-mediated signaling; regulation of calcium-mediated signaling; release of sequestered calcium ion into cytosol; release of sequestered calcium ion into cytosol by endoplasmic reticulum; response to hypoxia; calcium import into the mitochondrion; calcium ion transport; intrinsic apoptotic signaling pathway in response to endoplasmic reticulum stress; protein homotetramerization; regulation of autophagy; regulation of cytosolic calcium ion concentration; signal transduction; single fertilization; calcium ion transmembrane transport; calcium-mediated signaling; cell morphogenesis; epithelial fluid transport; monoatomic ion transport; phospholipase C-activating G protein-coupled acetylcholine receptor signaling pathway; phospholipase C-activating G protein-coupled receptor signaling pathway; positive regulation of apoptotic process; regulation of postsynaptic cytosolic calcium ion concentration; transmembrane transport
Cellular component: endoplasmic reticulum; endoplasmic reticulum membrane; membrane; platelet dense granule membrane; platelet dense tubular network; TCR signalosome; plasma membrane; platelet dense tubular network membrane; sarcoplasmic reticulum; secretory granule membrane; calcineurin complex; cytoplasm; nuclear envelope; nuclear inner membrane; nucleolus; perinuclear region of cytoplasm; postsynaptic density; protein-containing complex; Schaffer collateral - CA1 synapse; synapse; transport vesicle membrane
Genetic constraint (gnomAD): Loss-of-function variants: 65 observed, 245.83 expected, observed/expected ratio (o/e) 0.26, 90% interval 0.22 to 0.32. The upper end of that interval is the gene's LOEUF score, 0.32, which puts it in group 1 of 6, group 1 being the genes least tolerant of losing a copy. Missense variants: 2,071 observed, 3,004.7 expected, observed/expected ratio (o/e) 0.69, 90% interval 0.66 to 0.71. Synonymous variants: 1,112 observed, 1,136.4 expected, observed/expected ratio (o/e) 0.98, 90% interval 0.93 to 1.03.
Gene-disease validity (ClinGen):
ClinGen rates the evidence that ITPR1 causes each of these diseases.
aniridia-cerebellar ataxia-intellectual disability syndrome (autosomal dominant; autosomal recessive): Definitive. Aniridia-cerebellar ataxia-intellectual disability syndrome, also known as Gillespie syndrome, is a rare, congenital, neurological disorder characterized by the association of partial bilateral aniridia with non-progressive cerebellar ataxia, and intellectual disability.
spinocerebellar ataxia type 29 (autosomal dominant): Definitive. Spinocerebellar ataxia type 29 (SCA29) is a rare subtype of autosomal dominant cerebellar ataxia type I (ADCA type I) characterized by very slowly progressive or non-progressive ataxia, dysarthria, oculomotor abnormalities and intellectual disability.
Homologues: Orthologues: macaque ITPR1 (99% identical), dog ITPR1 (99% identical), rat Itpr1 (98% identical), mouse Itpr1 (98% identical), guinea pig ITPR1 (98% identical), rabbit ITPR1 (97% identical), pig ITPR1 (97% identical), chimpanzee ITPR1 (97% identical), tropical clawed frog itpr1 (89% identical), zebrafish itpr1b (86% identical), zebrafish itpr1a (82% identical), Drosophila melanogaster RyR (21% identical), and 1 more. Paralogues in human: ITPR2 (68% identical), ITPR3 (61% identical), RYR2 (24% identical), RYR1 (24% identical), RYR3 (24% identical).
Diseases named in the same sentence as ITPR1 in open-access papers:
ITPR1 is named in the same sentence as 211 diseases in open-access papers, as found by Europe PMC text mining. Sharing a sentence is not in itself a finding about the gene and the disease. The quoted sentences say what the papers report.
Ataxia (70 papers, 2009 to 2025). Ataxia refers to impaired coordination of voluntary muscle movement. "The 3p deletion involved four pathogenic genes (CHL1, CNTN6, CNTN4, ITPR1) associated with cognitive impairment, ataxia, and motor dysfunction." (PMID 41384039, 2025). "IP3R channel dysfunction has been associated with several disorders, such as spinocerebellar ataxia, Gillepsie syndrome, and generalized anhidrosis, mainly due to variants in ITPR1 and ITPR2." (PMID 39560673, 2025). "It is noteworthy that Itpr1, Calb1, Mtss1, and Kcnma1 are known to cause ataxia when mutated in human or mouse models." (PMID 38673939, 2024). "ITPR1-IgG/anti-Sj-associated ataxia thus forms part of a broader spectrum of anti-PC antibody-related ataxias referred to collectively as ‘medusa head ataxias’, based on the specific immunohistochemical staining pattern." (PMID 35907972, 2022). "Eleven patients showed very early-onset ataxia and CA with cortical hyperintensities caused by mutations in ITPR1, KIF1A, SPTBN2, PLA2G6, PMPCA, and PRDX3." (PMID 36233161, 2022). "A GGA-repeat expansion in the ITPR1-gene, which encodes a signalling molecule receptor that is highly expressed in the cerebellum, is associated with spinocerebellar ataxia in the Italian spinone." (PMID 35061740, 2022). "Clinical manifestation can be a mixture of typically associated syndromes, e.g. ataxia associated with anti-ITPR1 antibodies, encephalomyelitis with anti-GFAPα antibodies and longitudinal extensive myelitis with anti-MOG antibodies." (PMID 34635185, 2021). "Missense mutations of Itpr1 have been found in patients suffering from spinocerebellar ataxia, and cerebellum-specific deletion of Itpr1 in mice induces severe ataxia and synaptic loss, indicating the importance of ER calcium release for neuronal health." (PMID 33661276, 2021). "Research into Ca2+ signalling has found that non-synonymous mutations to ITPR1 have been linked with cerebellar ataxia in individuals as a result of the disturbances to ITPR1 associated Ca2+ signalling." (PMID 32316137, 2020). "Pathogenic mutations in ITPR1 were first described in two types of spinocerebellar ataxia (SCA), in which iris development is normal." (PMID 30242502, 2019). "Gillespie syndrome, which is a rare congenital disorder characterized by hypotonia, ataxia due to progressive cerebellar atrophy, and intellectual disability, is also caused by autosomal recessive or dominant missense mutations in ITPR1." (PMID 31658749, 2019). "This notion is exemplified by the findings that mutations in the gene encoding IP3R1, ITPR1, result in forms of spinocerebellar ataxia (SCA15 and SCA29) and Gillespie syndrome." (PMID 31658749, 2019). "SCA29 is also an autosomal dominant, pure cerebellar ataxia caused by an ITPR1 mutation, but with early-onset." (PMID 29196976, 2018). "ITPR1 mutation is an uncommon cause of inherited cerebellar ataxia, accounting for 0.2% (1/585) of patients with dominantly inherited cerebellar ataxias in Taiwan." (PMID 29186133, 2017). "This gene encodes a ligand-gated ion channel, an intracellular receptor for inositol 1,4,5-trisphosphate molecules which is highly expressed in neurons and deletions of Itpr1 are known to cause spinocerebellar ataxia." (PMID 28283027, 2017). "The clinical features of the individuals with ITPR1-associated cerebellar ataxia are quite heterogeneous." (PMID 29186133, 2017). "We identified a novel missense ITPR1 mutation, c.7721T>C (p.V2574A), in a patient with a slowly progressive cerebellar ataxia from 93 unrelated patients with molecularly unassigned SCA." (PMID 29186133, 2017). "The aim of this study was to investigate the role of ITPR1 mutations, including both large deletion and single nucleotide mutations, in a Han Chinese cohort with inherited cerebellar ataxias in Taiwan." (PMID 29186133, 2017).
Ataxia (continued). "The aim of this study was to investigate the role of ITPR1 mutations, including both large segmental deletion and single nucleotide mutations, in a Han Chinese cohort with inherited cerebellar ataxias in Taiwan." (PMID 29186133, 2017). "Although ITPR1 mutations have been identified in a small number of cases with inherited cerebellar ataxia, the relevant research in Han Chinese populations remains limited." (PMID 29186133, 2017). "This study broadens the mutational spectrum of ITPR1 and also emphasizes the importance of considering ITPR1 mutations as a potential cause of inherited cerebellar ataxias." (PMID 29186133, 2017). "Heterozygous mutations of ITPR1 are known to cause spinocerebellar ataxia (SCA) 15 [#606658] and 29 [#117360]." (PMID 28783747, 2017). "It is notable that the more severe and earlier-onset ITPR1-associated ataxia is caused predominantly by missense variants and that these missense variants are distinct from those associated with Gillespie syndrome." (PMID 27108798, 2016). "The confirmation of ITPR1 as an ataxia causing gene in humans led to the careful screening and discovery of mutations in SCA16 and SCA29 patients." (PMID 25055202, 2014). "RNF170 was shown to associate with inositol 1,4,5-triphosphate receptors (IP3), while mutations in its receptor, IP3R1 (ITPR1) also cause ataxia, providing a link between ubiquitination and ion channel signaling." (PMID 25055202, 2014). "Deletions of ITPR1 are known to cause spinocerebellar ataxia type 15, a distinct and very slowly progressive form of cerebellar ataxia with onset in adulthood." (PMID 22986007, 2012). "Mutation of Ip3r1 underlies ataxia in mice and mutations in ITPR1 have been identified in spinocerebellar ataxia 15 in humans." (PMID 19461874, 2009). "In conclusion, ITPR1‐related deletions are a rare cause of cerebellar ataxia." (PMID 41325768, 2025). "Furthermore, even ITPR1 leads to ataxia in both GLSP and SCAs; however, it only causes aniridia in GLSP, but rarely in SCAs." (PMID 39011359, 2024). "ITPR1 gene may be affected by loss-of-function mutations in some forms of spinocerebellar ataxia (SCA29)." (PMID 36712939, 2023). "In addition to these key functions during development, RORα is required throughout life to maintain PC dendrites and survival, for example ITPR1 deficiency causes the adult-onset spinocerebellar ataxia 15 with its associated PC loss." (PMID 37066074, 2023). "ITPR1 encodes a receptor for inositol 1,4,5-triphosphate (IP3), which mediates Ca2+ release from the endoplasmic reticulum upon stimulation, and mutations in ITPR1 are the cause of spinocerebellar ataxias; thus, the role of ITPR1 in the nervous system is well-established." (PMID 37373173, 2023). "The ITPR1-gene is also associated with spinocerebellar ataxia in humans." (PMID 35061740, 2022). "Notably, inactivating mutations in ITPR1 in both humans and mice result in spinocerebellar ataxia, illustrating the potential functional relevance of the affected genes to the cerebellar phenotype in the double-mutant mice." (PMID 34910524, 2021). "In mouse models of Itpr1 null alleles, heterozygosity elicits mildly impaired motor coordination and minor iris defects distinct from those of GS, and homozygosity is embryonic lethal or causes severe ataxia and seizures with early death." (PMID 30242502, 2019). "Mutations in the ITPR1 gene are associated with slowly progressive cerebellar ataxia." (PMID 29196976, 2018). "Mutations in ITPR1 have been implicated in a small group of patients with cerebellar ataxias and different ITPR1 mutations may result in similar but still distinguishable phenotypes." (PMID 29186133, 2017). "All these evidences support the association between ITPR1 mutations and cerebellar ataxia." (PMID 29186133, 2017).
Ataxia (continued). "Since these 93 patients were selected from a cohort of 585 unrelated patients with dominantly inherited cerebellar ataxias after a comprehensive genetic testing for SCA, mutation in ITPR1 accounts for 0.2% (1/585) of dominantly inherited cerebellar ataxias in Taiwan." (PMID 29186133, 2017). "ITPR1 missense mutation is an uncommon but unneglectable cause of cerebellar ataxia in Taiwan." (PMID 29186133, 2017). "These inter-familial and intra-familial heterogeneities suggest that there might be modifying factors underlying the pathogenesis of ITPR1-associated cerebellar ataxia." (PMID 29186133, 2017). "Mutations in ITPR1 have been implicated in inherited cerebellar ataxias." (PMID 29186133, 2017). "The ataxia, moreover, is less severe than in the mouse, due to incomplete loss of ITPR1 expression." (PMID 25354648, 2015). "Recently, it was reported that a deletion of the Itpr1 gene is associated with involuntary movements in patients of spinocerebellar ataxia type 15, which has been thought to be pure cerebellar ataxia." (PMID 24109434, 2013). "Itpr1 knockout mice either died in utero or had severe ataxia and epilepsy after birth, whereas Itpr2 knockouts had reduced sweat secretion and Itpr3 knockouts had abnormal taste perception." (PMID 39804930, 2025). "in an Australian family with pure cerebellar ataxia with deletions of exons 1–10 of ITPR1 and half of the SUMF1 gene." (PMID 41325768, 2025). "Spinocerebellar ataxia type 15 (SCA15), caused by deletions in the ITPR1 gene, is another potential genetic cause of SAN, as peripheral neuropathy is commonly associated with various spinocerebellar ataxias." (PMID 41325768, 2025). "ITPR1 is associated with hemifacial microsomia, ocular malformations such as the Gillespie syndrome (GLSP), and ataxia, depending on the variant of its mutation, indicating the remarkable allelic heterogeneity of this gene." (PMID 39011359, 2024). "ITPR1 (the gene involved in SCA15 and SCA29) missense mutations were detected in 6.66% (4/60) of patients with sporadic infantile-onset, cerebellar ataxia." (PMID 38911333, 2024). "Downregulated transcripts were found for the ATM interactome component Usp2, many non-coding RNAs, ataxia genes Itpr1, Grid2, immediate early genes and immunity factors." (PMID 37830614, 2023). "One compound appears as a selective potentiator of inositol triphosphate receptor type 1 (ITPR1) with a possible application for some forms of spinocerebellar ataxia." (PMID 36712939, 2023). "This paradox has already been described in other patients with ataxia and mutations in KIF1A, ITPR1, and PMPCA but also in KCNC3, and CACNA1A genes." (PMID 36233161, 2022). "While most mice carrying Itpr1 deletion die as embryos, the escapers exhibit severe ataxia and tonic-clonic seizures that lead to death by the weaning period." (PMID 35406743, 2022). "Homozygous deletion of Itpr1 in mice results in death in utero, with surviving mice displaying ataxia and epileptic seizures with death by the weaning period." (PMID 35757096, 2022). "Of note, signs of possible limbic involvement (confusion, severe memory loss, suspected temporal lobe epilepsy) were also present in two ITPR1-IgG/anti-Sj-seropositive patients identified by us in 2016, one of whom also had cerebellar ataxia." (PMID 35907972, 2022). "We find that splicing aberrations disrupt the expression of many key cerebellar PC genes, many of which (e.g., Itpr1, Grid2, Ca8, Bean1, etc.)can individually compromise cerebellar function and lead to ataxia." (PMID 34910524, 2021). "Because of high titres of ITPR1 antibodies in serum and CSF, she was closely followed up, and 11 years after onset of the ataxia, a clinically non‐manifest breast cancer (expressing ITPR1) was detected." (PMID 33816660, 2021). "A study reported that L7-Cre;Itpr1flox/flox mice, in which Itpr1 is deleted in Purkinje cells, exhibit cerebellar ataxia at around 6 weeks and severe ataxia at 8 weeks after birth." (PMID 32244264, 2020).